GSK3A (glycogen synthase kinase 3 alpha)
Diseases named in the same sentence as GSK3A in open-access papers (continued):
Sharing a sentence is not in itself a finding about the gene and the disease.
atherosclerosis (continued). "One of the suggested mechanisms linking ER stress to the development of atherosclerosis is mediated by the activation of glycogen synthase kinase (GSK)-3α/β." (PMID 29921793, 2018). "Together these findings strongly support a specific and direct role for GSK3α in the development of atherosclerosis." (PMID 29848965, 2018). "The same results were obtained with valproate, a GSK-3α/β inhibitor, suggesting that ER stress simulates progression of atherosclerosis through GSK-3." (PMID 29921793, 2018). "A second study focusing on GSK-3α showed that this isoform plays a role in atherosclerosis, a disease of the medium and large arteries in which arterial walls are inflamed and accumulate lipids." (PMID 28299185, 2017). "Similarly, GSK-3α was reported to promote lipid accumulation and accelerate atherosclerosis in a high-fat-diet mouse model." (PMID 40836599, 2025). "Recent studies support a role for GSK3α/β in atherosclerosis." (PMID 34394077, 2021). "The inhibition of GSK3A, PTP1B and BDKRB2 may be also associated with modulation of VaD risk factors, such as atherosclerosis and hypertension." (PMID 31937840, 2020). "Besides, increased P-STAT6 in GSK3α-null M2 cells was found, which underscored the role of GSK3α activation in shifting macrophages towards an M1 phenotype and promoted atherosclerosis." (PMID 30923552, 2019). "Inhibiting GSK-3α might attenuate atherosclerosis and promote M2 polarization." (PMID 30923552, 2019). "Further investigations are required to delineate direct upstream and downstream factors that link GSK3α/β to the JAK/STAT signaling pathways, as well as their role in the regulation of macrophage phenotype, particularly in the context of atherosclerosis." (PMID 29848965, 2018). "Further research has shown that a myeloid-specific knockout of GSK3α can also attenuate atherosclerosis, however not to the extent observed in the whole body GSK3α knockout mouse." (PMID 36499109, 2022). "Results from our lab suggest that myeloid deletion of GSK3α, but not GSK3β, attenuates the progression of atherosclerosis." (PMID 36012557, 2022). "Thus far, only a few studies have specifically examined GSK3α, including the functional elucidation of GSK3α in organ aging, ESC differentiation, atherosclerosis and hepatic steatosis, and hippocampal N-methyl-d-aspartate receptor-dependent long-term depression." (PMID 37031867, 2023).
melanoma (14 papers, 2012 to 2025). A malignant, usually aggressive tumor composed of atypical, neoplastic melanocytes. "A similar oncogenic role for miR-149 was also seen in melanoma in which upregulation of miR-149 causes downregulation of GSK3-α and upregulation of Mcl-1, resulting in apoptotic resistance." (PMID 23144691, 2012). "Indeed, we have also observed that inhibiting GSK3α/β in melanoma cell lines carrying a classical exon-3 mutation (β-catenin p.S37F) in the GSK3α/β consensus site did not have any effect on SOX10 protein levels." (PMID 32238882, 2020). "Decreasing GSK3A protein levels using siRNA and pharmacological targeting reduced melanoma tumor development in murine models." (PMID 40075679, 2025). "MiR-149 is another overexpressed miRNA in melanoma targeting GSK3a leading to apoptosis resistance in melanoma cells." (PMID 36224606, 2022). "In another study, pharmacologic inhibition of GSK3α/β was shown to reduce proliferation of melanoma cells and in vivo growth in a xenograft experiment." (PMID 32238882, 2020). "Here we describe a selective small molecule GSK3 inhibitor with potent in vitro activity against GSK3α and GSK3β with the ability to rapidly induce β-catenin dependent apoptosis in preclinical melanoma models." (PMID 25915038, 2015). "For instance, in melanoma upregulated miR-149 suppressed GSK3-α expression and upregulated Mcl-1 expression, resulting in apoptotic resistance." (PMID 23762558, 2013). "We also transfected M111031 melanoma cultures with a plasmid encoding either wild type β-catenin or a stabilized mutant p.S33Y that cannot be phosphorylated by GSK3α/β and thus not degraded by the proteasome." (PMID 32238882, 2020). "Our rescue and the RNA-sequencing experiments on the other hand demonstrate that the impairment of melanoma cell survival provoked by SOX10 suppression upon GSK3α/β inhibition is dependent on β-catenin, suggesting a direct involvement of canonical WNT/β-catenin signaling." (PMID 32238882, 2020). "From those findings, one might also conclude that the small subset of melanoma patients harboring a stabilizing exon-3 mutation may not derive benefit from treatment with GSK3α/β inhibitors." (PMID 32238882, 2020). "Thus, GSK3A could be a promising target for subtype-specific treatment in melanoma." (PMID 40075679, 2025). "Three independent inhibitors of GSK3α/β (CHIR99021, LY2090314, and AZD1080) inhibited SOX10 protein levels in a panel of human melanoma cell cultures." (PMID 32238882, 2020). "We demonstrate that inhibitors of glycogen synthase kinase 3 alpha/beta (GSK3α/β) efficiently abrogate SOX10 protein in human melanoma cells in vitro and in melanoma mouse models in vivo." (PMID 32238882, 2020). "Consistent with in vitro data, we demonstrate that temporal pharmacologic activation of WNT/β-catenin signaling by treatment with the GSK3α/β inhibitor CHIR99021 markedly decreases melanoma tumor growth by inhibiting proliferation and inducing apoptosis also in GEMM of melanoma." (PMID 32238882, 2020). "The selective GSK-3α and GSK-3β inhibitor LY2090314 shows very high cytotoxic activity in melanoma cells, both resistant and nonresistant to BRAF inhibitor." (PMID 29379583, 2017). "At variance, GSK3A, but not GSK3B, has been identified as a therapeutic target in melanoma suggesting that, similarly to what has been reported for normal cells, the two isoforms can play both distinct or redundant roles depending on the cancer cell type." (PMID 24984063, 2014). "Interestingly, previous studies in HeLa cells have shown that inhibition of GSK3A, but not GSK3B, enhanced sensitivity to TRAIL-mediated apoptosis, raising the possibility that some of the effects of CHIR99021 in our melanoma cells may be mediated through GSK3A." (PMID 23869245, 2013).
lung carcinoma (10 papers, 2016 to 2025). "Previous studies have linked GSK3A to neurodegenerative disorders and various cancers, including lung cancer." (PMID 40537285, 2025). "Tivantinib showed higher potency for GSK-3α more than for GSK-3β and the inhibition of GSK-3α or GSK-3β expression caused apoptosis in lung cancer cells." (PMID 27049759, 2016). "Knockdown of GSK-3α in lung cancer cells causes suppression of cell proliferation and also an induction of substantial apoptosis." (PMID 27049759, 2016). "We also found that overexpression of CREB mRNA level was associated with poor overall survival of lung cancer patients with very similar pattern for GSK3A mRNA." (PMID 27049759, 2016). "Overexpression of GSK3A mRNA levels was associated with poor overall survival of lung cancer patients (harzard ratio (HR) = 1.42, logrank P = 4.9e-06)." (PMID 27049759, 2016). "Our results on clinical tumor samples demonstrate that aberrant activation of GSK-3α is associated with human mortality of lung cancer patients, especially with lung adenocarcinoma." (PMID 27049759, 2016). "Interestingly, GSK3A mRNA levels were more strongly associated with poor overall survival of lung cancer patients with adenocarcinoma (HR = 1.99, logrank P = 2.4e-06)." (PMID 27049759, 2016). "The observations that GSK-3α expression plays a causal role in survival of lung cancer patients, suggest GSK-3α could be useful as a prognostic biomarker in lung cancer, especially lung adenocarcinoma." (PMID 27049759, 2016). "On the other hand, there has been no report regarding the role of GSK3A in gastric cancer, although GSK3A was shown to promote the survival of lung cancer cells, and both GSK3A and GSK3B are abnormally activated in non‐type bladder cancer cells." (PMID 36520032, 2023). "Results of the present study demonstrated that GSK3α was significantly upregulated in lung cancer patients, who subsequently exhibited shorter survival times." (PMID 35292059, 2022). "The analysis of the H1993 and H1437 lung cancer cell lines demonstrated that the transfection with shRNA against GSK3α or CREB, reduced cell viability and increased apoptosis." (PMID 33339170, 2020). "In this study, a positive GSK3α-dependent expression mechanism of cyclins A2, B1, D1, and E2 was uncovered and found to be correlated with the reduced proliferation of lung cancer cells via GSK3α inhibition." (PMID 33339170, 2020). "We have previously shown in lung cancer cells that GSK3α and to a lesser extent GSK3β are inhibited by the advanced clinical candidate tivantinib (ARQ197), which was designed as a MET inhibitor." (PMID 30679640, 2019). "Kaplan-Meier analysis with a public database showed a prognostic significance of aberrant GSK-3α expression in lung cancer." (PMID 27049759, 2016). "Although the overexpression of GSK-3β and its function as a tumor promoter in lung cancer has been demonstrated, the role of GSK-3α in lung cancer remains elusive." (PMID 27049759, 2016). "Next, knockdown of GSK-3α with its specific siRNA resulted in a decrease in the viability of all lung cancer cell lines we tested." (PMID 27049759, 2016). "Here, we found that GSK-3α is overexpressed in multiple lung cancer cell lines compared with NHTBE cells." (PMID 27049759, 2016). "Here, we identified GSK-3α as one of the CREB target genes which is critical for the viability of lung cancer cells." (PMID 27049759, 2016). "The validation of siRNAs or shRNAs on the expression of GSK-3α was performed by qPCR or western blot analysis in multiple lung cancer cell lines." (PMID 27049759, 2016). "Further studies examining the mechanisms for targeting CREB-GSK-3α pathway in lung cancer will be essential for determining and developing the GSK-3α specific inhibitors." (PMID 27049759, 2016). "Though our study did not directly identify how cyclins are regulated by GSK-3α, these results strongly support the novel role of GSK-3α as an active regulator in the viability of lung cancer cells." (PMID 27049759, 2016).
lung carcinoma (continued). "Taken together, we suggest that CREB is a potential upstream regulator of GSK-3α in lung cancer cells." (PMID 27049759, 2016). "The protein expression of several cyclins including cyclin A2, cyclin B1, cyclin D1, and cyclin E2 was markedly suppressed by GSK-3α knockdown in lung cancer cell lines." (PMID 27049759, 2016). "For the first time, we demonstrated that GSK-3α is regulated by CREB in lung cancer and is required for the cell viability." (PMID 27049759, 2016). "In our current study, we found that GSK-3α is overexpressed in lung cancer cell lines compared to normal bronchial epithelial cells." (PMID 27049759, 2016). "Here, our results show that decreased levels of GSK-3α impair the viability of lung cancer cells in vitro and in vivo." (PMID 27049759, 2016). "Aberrant expression of GSK3α in lung cancer has prognostic significance for clinical treatment." (PMID 33879767, 2021). "Tivantinib was shown to inhibit GSK3α and to a lesser extent GSK3β in lung cancer cells." (PMID 32887519, 2020). "Although it remains unclear whether KRAS status is directly related to the role of GSK-3α in lung cancer cells, we suggest that the function of GSK-3α in KRAS signaling might be regulated in a cell-type specific manner." (PMID 27049759, 2016). "Taken together, these results suggested that GSK-3α might function positively in the viability of lung cancer cells by regulating the expression of cyclins." (PMID 27049759, 2016). "To gain insight into the role of GSK-3α in lung cancer cell viability, we first examined whether GSK-3α regulates cell cycle using FACS analysis." (PMID 27049759, 2016). "Consequently, GSK-3α knockdown significantly suppressed the cell viability of KRAS-WT lung cancer cell lines (H1993 and H1437), compared to KRAS-mutant lung cancer cell lines (H1734 and A549)." (PMID 27049759, 2016). "GSK-3α is overexpressed in multiple lung cancer cell lines and lung tumor tissues." (PMID 27049759, 2016). "Furthermore, we examined that there is a positive correlation between high GSK-3α expression and shorter survival of lung cancer patients." (PMID 27049759, 2016). "Interestingly, our study showed that the GSK-3α knockdown highly suppressed the cell viability of KRAS-WT lung cancer cell lines, H1993 and H1437 cells, compared to KRAS-mutant lung cancer cell lines, H1734 (G13C) and A549 (G12S) cells." (PMID 27049759, 2016). "In this study, we first identified GSK-3α as a novel target of CREB in lung cancer cells." (PMID 27049759, 2016). "In addition, the protein expression of GSK-3α was dramatically suppressed by CREB knockdown in all four lung cancer cell lines we tested but the protein level of GSK-3β was not changed by CREB knockdown." (PMID 27049759, 2016). "Additionally, we found that the expression of several cyclins which are known as CREB target gens was markedly downregulated by GSK-3α knockdown in multiple lung cancer cell lines." (PMID 27049759, 2016). "The mechanism of GSK-3α as a tumor promoter in lung cancer is virtually unknown." (PMID 27049759, 2016). "However, the role of GSK-3α in lung cancer still need more investigation." (PMID 27049759, 2016). "Interestingly, GSK-3α knockdown suppressed S phase of the cell cycle, which might contribute the reduced cell viability of lung cancer cells." (PMID 27049759, 2016). "The results showed that the activity of AKT was positively correlated with the level of p-GSK-3α and that the activity of AKT in A549 and A549/DDP lung cancer cells was significantly reduced when the cells received both treatment schemes." (PMID 28969040, 2017). "The effects of T4, wortmannin, perifosine and rapamycin on the expression of p-GSK-3α showed the same trend in both A549 and A549/DDP lung cancer cells." (PMID 28969040, 2017). "However, the role of GSK-3α in lung cancer still largely remains unknown." (PMID 27049759, 2016).
lung carcinoma (continued). "Together, these findings implicates that GSK-3α is a critical target gene of CREB and CREB-GSK-3α signaling is a potential therapeutic target for lung cancer." (PMID 27049759, 2016). "To determine the effect of GSK-3α, which is a CREB target gene, we confirmed the effect of CREB knockdown on the cell viability in multiple lung cancer cell lines." (PMID 27049759, 2016). "Our study reveals oncogenic roles of GSK-3α as a CREB target gene and as a novel prognostic biomarker in lung cancer." (PMID 27049759, 2016). "In conclusion, we propose that GSK-3α is a promising therapeutic target as a novel target gene of CREB to diagnose tumor and develop the therapy, with relevance for lung cancer." (PMID 27049759, 2016). "Recently, GSK-3α and GSK-3β have been reported to be new kinase targets of tivantinib, which is a potent selective inhibitor of the receptor tyrosine kinase c-MET, in lung cancer cells." (PMID 27049759, 2016). "However, the KRAS/GSK3α/NF-κB axis has not been tested in a lung cancer environment." (PMID 33339170, 2020). "Although the functional consequence of CREB activity by GSK-3 is not still clear, our study strongly suggests that CREB positively regulates GSK-3α, not GSK-3β, in lung cancer cells, thus providing a new concept of CREB-GSK-3α signaling." (PMID 27049759, 2016). "More importantly, CREB regulates the expression of GSK-3α but not GSK-3β, suggesting that there is a specific arm of CREB-GSK-3α signaling in lung cancer." (PMID 27049759, 2016). "We found that the mRNA level of GSK-3α, not the level of GSK-3β, was significantly downregulated by CREB siRNA in all lung cancer cell lines we tested (H1993, H1437, H1734, and A549)." (PMID 27049759, 2016). "Here, we first identified that GSK-3α, not GSK-3β, is regulated by CREB in lung cancer cells." (PMID 27049759, 2016).
breast carcinoma (8 papers, 2013 to 2024). "In summary, we have demonstrated that mitochondrially targeted iron chelators, mitoDFO and mitoDFX, upregulate NDRG1 expression and induce Thr346 phosphorylation via the GSK3α/β kinase in breast cancer cells." (PMID 38983911, 2024). "Pharmacological inhibition of GSK3 with CHIR99021 or silencing of GSK3α/β using siRNAs resulted in elevated BOK protein levels in breast cancer cells." (PMID 29156771, 2017). "Supporting this, we identified several potential GSK3 phosphorylation sites on BOK protein and showed that the inhibition of GSK3α/β led to increased expression of BOK in breast cancer cells." (PMID 29156771, 2017). "In addition to miR-296-5p, we demonstrate that glycogen synthase kinases 3 α/β (GSK3α/β) regulate BOK expression by physically interacting with BOK in breast cancer cells." (PMID 29156771, 2017). "The top five CTRP hits in rank order include ML239 (breast cancer stem cell inhibitor), Niclosamide (anti tapeworm drug), Tipifarnib (H-Ras inhibitor), CHIR-99021 (GSK-3α/β inhibitor), and Tivantinib (MET inhibitor)." (PMID 36672285, 2023). "Moreover, overexpression of either GSK-3α or GSK-3β activates mTORC1 and suppresses autophagy in breast cancer cells." (PMID 31882719, 2019).
Insulin resistance (8 papers, 2011 to 2025). Increased resistance towards insulin, that is, diminished effectiveness of insulin in reducing blood glucose levels. "The results demonstrate insulin resistance, further aggravated by PP1γ, caused AD-like phenotype however, through a phenomenon of oppositely regulating phosphorylation of GSK3α and GSK3β isoforms wherein one promotes AD-like phenotypes while the other prevent it." (PMID 37085815, 2023). "We speculate that the beneficial effect of GSK-3α inhibition is associated with the genetic/environmental susceptibility of insulin resistance within these rodent strains." (PMID 21253590, 2011). "The inhibition of GSK3A improves insulin response, suggesting possible beneficial effects on insulin resistance, metabolic syndrome, and diabetes." (PMID 40807372, 2025). "Beside impaired glucose metabolism, VIC develop an insulin resistance upon HI and HG with disturbed Akt/GSK-3α/β signaling, whilst HG alone was sufficient to induce insulin resistance." (PMID 36386326, 2022). "Under conditions of insulin resistance, the activity of the GSK-3α in skeletal muscle, and liver is enhanced." (PMID 31164832, 2019). "Visfatin reduced the levels of insulin-signaling proteins, including p-IR, p-IRS-1 (Tyr612), p-AKT, and p-GSK-3α/β, triggering insulin resistance." (PMID 31396538, 2019). "To investigate whether galangin can get insulin resistance better, we examined the phosphorylation state of ten proteins on the Akt/mTOR signal pathway, including IR, IRS1, PTEN, Akt, GSK3α, GSK3β, TSC2, mTOR, p70S6K, and RPS6." (PMID 30420897, 2018).